FBN1 (fibrillin 1)
Diseases named in the same sentence as FBN1 in open-access papers (continued):
Sharing a sentence is not in itself a finding about the gene and the disease.
Marfan syndrome (continued). "Other ocular diseases that affect the elastic component, and more specifically the microfibrils of FBN1, include myopia and ectopia lentis; both ophthalmological pathologies are frequently observed in Marfan syndrome, which involves defects in the microfibrils of FBN1." (PMID 34945227, 2021). "Here, we propose that personalised medicines using antisense oligonucleotides (AO) to alter FBN1 exon selection during the splicing process, may be an appropriate therapeutic approach for some individuals with Marfan syndrome." (PMID 33801742, 2021). "In a Marfan syndrome patient, the disease-causing FBN1 mutation results in a lack of functional microfibrils, in turn leading to instability of the ECM that is further compounded by the dysregulation of TGF-β." (PMID 33801742, 2021). "Such abnormalities were rescued by gene editing of FBN1 mutation by CRISPR/Cas9, which identified the role of p38 mitogen-activated protein kinase and KLF4 in regulation of vSMC proliferation and apoptosis that leads to the pathology of Marfan syndrome." (PMID 31871214, 2020). "Three different variations, NM_000138.4( FBN1 ):c.229G > A(p.Gly77Arg), NM_000138.4( FBN1 ):c.165-2A > G (novel), NM_000138.4( FBN1 ):c.399delC (p.Cys134ValfsTer8) (novel) were determined in our three cases referred with a prediagnosis of Marfan syndrome." (PMID 32939518, 2020). "In addition to fibrillin-1 mutations, transforming growth factor β receptor 2 (TGFBR2) and TGFBR1 also cause Marfan syndrome and these pathways regulate ECM synthesis and homeostasis." (PMID 33228202, 2020). "Marfan syndrome (MFS) (OMIM #154700, ORPHA #284963) is an inherited connective tissue disorder caused by pathogenic variants in the fibrillin-1 gene (FBN1), encoding for the extracellular matrix protein, fibrillin-1." (PMID 33097072, 2020). "Marfan syndrome (MFS; MIM #154700) refers to a heritable autosomal dominant disease trait of fibrous connective tissue due to heterozygous mutations in the fibrillin‐1 gene (FBN1; MIM #134797) on chromosome 15q21." (PMID 31774634, 2020). "Gene defects in fibrillin-1 give rise to Marfan syndrome (MFS; OMIM #154700)." (PMID 31805661, 2019). "According to the literature, FBN1 is the only major gene involved in Marfan Syndrome." (PMID 31065451, 2019). "Indeed, the most prominent TAA aetiology in our two human cohorts is the bicuspid aortic valve, which shows common (fbn1 gene expression decrease, immaturity of aortic wall) but also different histologic modifications compared to the Marfan syndrome." (PMID 31409059, 2019). "Heterozygous MgΔ mice, another mice model of Marfan syndrome, show half level of Fbn1 as WT mice." (PMID 30585249, 2018). "Many genes encoding collagen, Timps and other proteins known to be involved in connective tissue diseases such as EDS and Marfan syndrome, including Adamts2, Fbn1 and Fbn2, had more than a 4-fold decreased expression in Zeb2-cKO fibroblasts compared with wild-type fibroblasts." (PMID 28422173, 2017). "Another possible explanation is that aneurysms in Marfan syndrome are caused by a disturbance of signaling maintained by fibrillin-1, and not by defects in microfibril structure per se." (PMID 28252045, 2017). "The clinical diagnosis of Marfan syndrome was established and these children underwent genetic analysis to detect mutation in the FBN1 gene which revealed negative in all cases." (PMID 26858800, 2016). "In a mouse model of Marfan syndrome, many of the phenotypic effects have been attributed to function of fibrillin-1 in regulating the bioavailability of transforming growth factor β (TGFβ) family members, (including activins and bone morphogenic proteins) which inhibit adipogenesis." (PMID 27386756, 2016). "Marfan syndrome is associated with mutations or deletions in FBN1 at 15q21.1, but the index patient did not have molecular confirmation of the diagnosis." (PMID 27239352, 2016).
Marfan syndrome (continued). "Marfan syndrome (MFS) is an autosomal dominant disease of the connective tissue, affecting mostly the skeletal, ocular and cardiovascular systems, caused by mutations in the FBN1 gene." (PMID 26927851, 2016). "Inability to detect a mutation in FBN1 or a molecular abnormality in fibrillin-1 does not exclude the diagnosis of Marfan syndrome in a person who meets the clinical criteria." (PMID 28050285, 2016). "Three VUS variants in FBN1 (p.Tyr20Cys, p.Ala1152Val, and p.Glu2019Lys) were previously reported in patients with Marfan syndrome, without sufficient evidence to be classified as likely pathogenic." (PMID 26017485, 2015). "Furthermore, alternative splicing of FBN1 has been suggested to modulate the severity of Marfan syndrome." (PMID 25798732, 2015). "Because alteration in body size is a prominent indicator of Marfan syndrome, it suggests that connective tissue-like tissue integrity mediated by mua-3 or fbn-1 could be related to TGFβ signaling pathways in C." (PMID 25917920, 2015). "The Marfan syndrome gene, FBN1, was localized on chromosome 15q21 and cloned in 1991." (PMID 24484584, 2014). "Marfan syndrome (MFS) and congenital contractural arachnodactyly were the first diseases to be linked to the human FBN1 and FBN2 genes, respectively, which encode the fibrillin-1 and fibrillin-2 isoforms." (PMID 24035709, 2013). "These genes may be hereditary determinants like FBN1 in Marfan syndrome, or be involved in the pathogenesis of aortic dilatation in the context of congenital aortic valve malformations." (PMID 23326585, 2013). "Since the FBN-1 gene is a large gene with 65 exons, screening and mutation detection for Marfan syndrome are not cost-effective methods." (PMID 23493941, 2012). "The FBN-1 mutation is not specific to Marfan syndrome, and the absence of mutation in this gene does not rule out the diagnosis of Marfan syndrome." (PMID 23493941, 2012). "In the fibrillin-1 mouse model of Marfan syndrome that recapitulates the TAA phenotype, increased TGF-beta signaling has been shown to have a major role in pathogenesis, and Losartan, an angiotensin receptor blocker (ARB) that also antagonizes TGF-beta, rescues TAA." (PMID 22970404, 2012). "The pathogenesis of Marfan's syndrome has not been fully elucidated, but fibrillin-1 gene mutations are believed to exert a dominant negative effect through excessive TGF-β signaling pathways." (PMID 21308160, 2010). "In patients with Marfan syndrome (MFS), a positive correlation was observed between FBN1 expression and the diameter of the sinotubular junction." (PMID 40243722, 2025). "Among these, Marfan syndrome (MFS) is one of the most prevalent connective tissue disorders, caused by mutations in the FBN1 gene, which encodes the ECM protein, Fibrillin-1." (PMID 40497944, 2025). "Marfan syndrome (MFS; OMIM #154700) is a typical inherited connective tissue disease caused by mutations in FBN1 that shows autosomal dominant (AD) inheritance." (PMID 39939800, 2025). "However, variants in the FBN1 gene were identified in healthy individuals, suggesting that its presence does not necessarily translate to Marfan syndrome development." (PMID 41463310, 2025). "However, FBN1's direct functional role in the adult brain remains underexplored, with most research focusing on its structural role in connective tissue disorders such as Marfan syndrome." (PMID 41399726, 2025). "Pathogenic variants in FBN1 impair the formation of microfibrils, leading to the production of abnormal connective tissues, resulting in Marfan syndrome (MFS) (MIM:154700), the most common inherited disease caused by FBN1 pathogenic variants." (PMID 38791509, 2024). "Marfan syndrome (MFS) is an autosomal dominant, highly penetrant condition that is caused by pathogenic variants in FBN1, which encodes fibrillin-1, a major structural component of extracellular matrix in connective tissues." (PMID 38673024, 2024).
Marfan syndrome (continued). "Fibrillin-1 and fibrillin-2, encoded by FBN1 and FBN2, respectively, play significant roles in elastic fiber assembly, with pathogenic variants causing a diverse group of connective tissue disorders such as Marfan syndrome (MFS) and congenital contractural arachnodactyly (CCD)." (PMID 38791509, 2024). "It is well known that Marfan syndrome (MFS) was first reported in 1896, and the fibrillin‐1 (FBN1) gene was first isolated from cDNA clones in 1991." (PMID 39219382, 2024). "Marfan syndrome (MFS) is a hereditary condition accompanied by disorders in the structural and regulatory properties of connective tissue, including elastic fibers, due to a mutation in the gene encodes for fibrillin-1 protein (FBN1 gene) and the synthesis of abnormal fibrillin-1 glycoprotein." (PMID 39273142, 2024). "Marfan syndrome (MFS) is a connective tissue disorder caused by mutations in the FBN1 gene, which codes for the extracellular glycoprotein fibrillin-1." (PMID 37894814, 2023). "Besides FBN1, mutations in the transforming growth factor-β receptor 1 (TGFBR1) and transforming growth factor-β receptor 2 (TGFBR2) may also be found in Marfan syndrome." (PMID 37441579, 2023). "This deletion affects exons 42–45 of the FBN1 gene and results in neonatal Marfan syndrome (nMFS), a severe form of Marfan syndrome (MFS, OMIM: 154700)." (PMID 38016949, 2023). "The best characterized genes include FBN1 [Marfan syndrome (MFS)], TGFBR1 and TGFBR2 [Loeys-Dietz syndrome (LDS)], SMAD3 [aneurysm-osteoarthritis syndrome (AOS)], and ACTA2 [Aortic and Cerebral Aneurysm (ACA)]." (PMID 36312254, 2022). "Although the FBN1 variant in our patient has been reported and considered as a pathogenic variant, no other features of Marfan Syndrome such as dolichostenomelia, arachnodactyly, joint laxity, velvety skin, ectopia lentis and cardiovascular manifestations were identified." (PMID 35346302, 2022). "However, at the aged of 27 years, not having a causative mutation for Marfan’s Syndrome in the Fibrillin-1 gene, skin biopsy was performed and confirmed CBS deficiency consistent with classical HCU." (PMID 35342812, 2021). "Another study suggests the possibility of using ADAMTSL6-mediated fibrillin-1 microfibril assembly as a therapeutic tool to rescue the cells of Marfan syndrome (MFS)." (PMID 35053160, 2021). "Regarding the superior prevalence of BAV in patients with Marfan syndrome to the general population, common underlying mechanisms for these two entities have been proposed: increased metalloproteinase (MMP) activity and a decreased fibrillin-1 expression in the aortic wall." (PMID 34071740, 2021). "Modifiers of penetrance and phenotypic expressivity in Marfan syndrome have been previously proposed and a study based on a single Marfan syndrome family also suggested that differences in normal FBN1 expression could contribute to the clinical variability of Marfan syndrome." (PMID 33226994, 2020). "Marfan syndrome (MFS) is a rare connective tissue disorder attributed to a defect in the fibrillin-1 gene." (PMID 32158563, 2020). "Even if kidney disease is not described in the Marfan syndrome and even if the renal structure is similar between the Wt and Fbn1C1041G/+ mice, we cannot exclude that the alteration of miR-574-5p expression in the kidney is not a consequence of fbn1 mutation." (PMID 31409059, 2019). "Defects in the extracellular matrix protein fibrillin-1 that perturb transforming growth factor beta (TGFβ) bioavailability lead to Marfan syndrome (MFS)." (PMID 31805661, 2019). "The isolated aortic root dilation we observed in our cohort is similar to that seen in Marfan syndrome (MFS, OMIM 154700), a disease caused in most cases by mutations in the FBN1 gene, that encodes fibrillin-1, but to a lesser degree." (PMID 28980096, 2018).
Marfan syndrome (continued). "Although BAV and Marfan syndrome (MFS) share some clinical features, and some MFS patients with BAV display mutations in FBN1, the gene encoding fibrillin-1, the genetic background of isolated BAV is poorly defined." (PMID 24564502, 2014). "Marfan Syndrome (MFS) and Loeys-Dietz Syndrome (LDS), caused respectively by mutations in fibrillin-1 and TGF-β receptors I and II, predispose to ascending thoracic aortic aneurysms (TAAs), but are much less often associated with AAA." (PMID 23852016, 2013). "Interestingly, absence of Fbn-1 is associated with Marfan's syndrome, and over expression leads to myocardial fibrosis." (PMID 23738044, 2013). "In addition to the typical clinical findings of the Marfan syndrome due to FBN1 gene haploinsufficiency, the patient presents features which may be due to the other gene deletions and possibly to the complex chromosome rearrangement." (PMID 22260333, 2012). "Our data expand the number of large FBN1 deletions, and emphasize the importance of screening for large genomic deletions in comprehensive genetic testing for connective tissue disorders featuring aortopathies, especially for those with classic phenotype of Marfan syndrome." (PMID 21936929, 2011). "Fbn1-null mutants do display the vascular abnormalities that have been associated with Marfan's syndrome but they do not appear to manifest most other symptoms seen in humans with the condition, while reported Fbn2-null mutants do not fully recapitulate the CCA phenotype." (PMID 20161761, 2010). "For example, Marfan syndrome, a connective tissue disorder in which the walls of major arteries are weakened, leading to aneurysm, has been linked to mutation of the FBN1 gene on chromosome 15 that encodes for fibrillin-1, which is an essential component of elastic fibers in connective tissue." (PMID 17311093, 2007). "Mutations in FBN3 as well as in two other family members of the fibrillin-family FBN1 and FBN2 have been identified in several disorders, including Bardet–Biedl syndrome and Marfan syndrome." (PMID 41440000, 2025). "Mouse models of Marfan syndrome have demonstrated increased TGF-β/Smad signaling in myxomatous valve pathophysiology, consistent with a role for FBN1 in limiting TGF-β activity in the extracellular matrix." (PMID 40519164, 2025). "A more comprehensive understanding of the disease would require detailed genetic characterization beyond FBN1, including TGFB2, its receptors (TGFBR1, TGFBR2), and other genes involved in Marfan syndrome and related disorders." (PMID 40243722, 2025). "For Marfan syndrome, PERADIGM identified eight genes, significantly broadening the genetic landscape beyond FBN1." (PMID 41411243, 2025). "Historically, genetic testing focused on core syndromic genes, such as FBN1, TGFBR1/2, and COL3A1, which collectively account for the majority of diagnoses in classic connective tissue disorders like Marfan syndrome, LDS, and vEDS." (PMID 40981152, 2025). "Canonical syndromic genes, such as FBN1 and COL3A1, are highly penetrant and account for the majority of Marfan syndrome and vascular Ehlers–Danlos cases, respectively." (PMID 40981152, 2025). "Currently, rare variants and polymorphisms in FBN1 (OMIM∗134797), which cause Marfan syndrome (MFS), have also been reported to be involved in nonsyndromic TAAD; however, when assessing the pathogenicity of unclassified variants, it is important to ensure that preventive measures are taken." (PMID 39185084, 2024). "Marfan syndrome (MFS), a connective tissue disorder with a wide range of musculoskeletal and cardiovascular alterations, is caused mainly by mutations in FBN1 gene, which codes for Fibrillin-1, an ECM structural protein which polymerizes into microfibrils." (PMID 33297501, 2020).
Marfan syndrome (continued). "However, the scarce studies of SCD do not use current criteria of Marfan syndrome, they do not document presence of causative FBN1 mutations, and they do not investigate the role of different types of FBN1 mutations on the risk of ventricular arrhythmia and SCD." (PMID 24349050, 2013). "Because of phenotypic similarities with the connective tissue disorders frequently observed in Marfan syndrome, it is likely that HCU involves impairment of fibrillin-1 function." (PMID 20638882, 2010). "Although The Fbn1+/Q2469X mouse model does not reproduce the full spectrum of Marfan syndrome, it offers a genetically defined system in which late-stage aneurysm progression can be examined with consistency." (PMID 41040364, 2025). "Therefore, our objective was to assess the mRNA expression of FBN1, TGFBR1, TGFBR2, and TGFB2 in the aortic tissue of Marfan syndrome patients with aortic dilation." (PMID 40243722, 2025). "Altered MFAP4 glycosylation could potentially affect binding to elastogenic proteins, including fibrillin-1 or LTBP4 isoforms, possibly affecting formation and maintenance of microfibrils and elastic fibres, which are compromised in Marfan syndrome." (PMID 38740766, 2024). "The presence of ectopia lentis was highly suggestive of the implication of the FBN1 gene since this clinical feature is not one of the other Marfan syndrome genes." (PMID 36926521, 2023). "Previous genetic investigations, consisting of Sanger sequencing and MLPA techniques of FBN1, panel genes of Marfan syndrome and related diseases, array-CGH, and ES solo were negative." (PMID 36926521, 2023). "It is estimated that in more than 20% of TAAD a hereditary background with fibrillin-1 (Marfan syndrome) or other autosomal dominant disorders without syndromic features can be found in familial TAAD." (PMID 35050224, 2022). "In April 2017, she was referred to our hospital and was diagnosed with Marfan syndrome (MFS) based on the presence of ectopia lentis and TAAD and a previously reported FBN1 pathogenic variant (c.1709G>C; p.Cys570Ser); however, she died suddenly due to an unknown cause a few months later." (PMID 35957784, 2022). "We also found a common FBN1 linkage group that is associated with TAA and aortic dissection in patients who do not have Marfan syndrome." (PMID 34469433, 2021). "Thus, Marfan syndrome was considered, and a UDN bioinformatician manually inspected the FBN1 gene in the GS data." (PMID 32730690, 2020). "The highest number of VLP/Ps (n = 94) were reported in both MYBPC3 (MIM: 600,958; definitive for hypertrophic and dilated cardiomyopathies[HCM/DCM]) and FBN1 (MIM: 134,797; definitive for Marfan syndrome), accounting for 60% and 51% of the total reported findings for these genes, respectively." (PMID 30900393, 2019). "To gain insights into the ocular sequelae of Marfan syndrome, we targeted Fbn1 in mouse lens or non-pigmented ciliary epithelium (NPCE)." (PMID 30642872, 2019). "Patients fulfilling the criteria for Marfan syndrome (MFS) were only included if targeted FBN1 sequencing and MLPA analysis were negative." (PMID 25644172, 2015). "Moreover, as supported by the literature, several have been associated with hernia formation, Ehlers–Danlos syndrome, and Marfan’s syndrome (e.g., COL1A1, COL3A1, COL5A1, FBN1, and TIMP1)." (PMID 22648066, 2013). "In all other patients, including a 27-year-old male with classical Marfan syndrome phenotype (patient 14), no large deletions or duplications of the FBN1, TGFβR1, and TGFβR2 genes were identified." (PMID 21936929, 2011). "Although the oldest Morrocan child (14 years old) had tall stature and a narrow face suggestive of Marfan syndrome, other Marfan syndrome criteria were not met and fibrillin-1 testing was negative." (PMID 22025892, 2011). "Abnormal fibrillin-1 may contribute to atypical lens development, accounting for such non-classical cataract patterns in Marfan syndrome." (PMID 41971218, 2025).